IL6 (interleukin 6)
Diseases named in the same sentence as IL6 in open-access papers (continued):
Sharing a sentence is not in itself a finding about the gene and the disease.
cancer (continued). "Cancer promotion can be regulated by several pathways associated with inflammation, such as those involving NF-κB, STAT3, mTOR, and MAPKs, which are triggered by pro-inflammatory cytokines like IL-6, TNF-α, and IL-1β." (PMID 34950252, 2021). "IL-6 is produced by cancer cells, as well as inflammatory and stromal cells." (PMID 34445405, 2021). "However, increased serum level of IL-6 are both due to the direct production of cancer cells and (and above all) to the monocytes’ production." (PMID 34944975, 2021). "As previously reported, the malignant tumors incite a systemic inflammatory response, which often triggers the release of inflammatory cytokines and chemokines, such as tumor necrosis factor and IL-1 and IL-6." (PMID 34917503, 2021). "Additionally, epithelial-to-mesenchymal transition, important in cancer cell invasiveness, metastatic potential, and cell detachment, is facilitated via IL-1, IL-6, and STAT3 signaling in chronic inflammation." (PMID 34988471, 2021). "IL-6 inhibition could help sustain the limited anti-cancer immune responses normally induced by cytotoxic agents in the clinic." (PMID 34711820, 2021). "In addition, cancer-associated fibroblasts (CAFs) are able to secrete chemokines and cytokines, such as TGFβ, CXCL12, VEGF, and IL6, which stimulate cancer cell proliferation, epithelial–mesenchymal transition, and migration." (PMID 34868991, 2021). "Clinical trials targeting CAF associated pathways involving IL-6 and TGF-β in different cancers." (PMID 34094963, 2021). "In addition, IL-6 secreted from cancer cells facilitates angiogenesis and stromal changes to the CAF phenotype, increasing the levels of matrix metalloproteinase-2 and -9 (MMP-2 and MMP-9), which trigger ECM proteolysis." (PMID 34957091, 2021). "For example, IL-6 overproduction by stromal cells supports tumor growth through STAT3 activation, promotes cancer-associated fibroblast (CAF)-induced cancer invasion, and was recently shown to promote resistance of cancer cells to therapy, proving its broad pro-tumorigenic role." (PMID 33923020, 2021). "Notably, IL-6 represents the most investigated cytokine regulating the crosstalk between CAFs and cancer cells." (PMID 34108441, 2021). "Furthermore, the novel extract sufficiently adjusted the production of proinflammatory cytokines including TNF-α, TGF-β, IL-6, and IL-8, which play a crucial role in inflammatory events and cancer development." (PMID 34513674, 2021). "Interleukin 6 (IL-6) is an important interleukin that acts in a dual directional regulation manner, pro-inflammatory and anti-inflammatory, which has been confirmed to play crucial roles in various inflammation related conditions including cancers." (PMID 34689842, 2021). "TGF-β and IL-6 have been recognized as key drivers in several carcinomas." (PMID 33567693, 2021). "Importantly, IL-6 has been demonstrated to have a strong impact on the early progression to carcinoma in IBD via STAT3 signaling." (PMID 34884543, 2021). "Moreover, IL-6 expression was found to be related to CLU production in cancer cells and neoplastic tissues." (PMID 32516132, 2020). "Studies have proved that Bazedoxifene inhibits IL‐6/gp130 signalling pathway in several types of cancer, but whether the observed benefit of Bazedoxifene intake is dependent of IL‐6 signalling in pressure overload mice has not been established." (PMID 32164044, 2020). "Regarding IL6, such analyses determined that an IL6 value below 2.9 pg/mL showed an 80% likelihood of survival versus values above 2.0 pg/mL demonstrating an 80% chance of cancer-related death." (PMID 33066437, 2020). "In cancer patients, release of proinflammatory cytokines (IL‐6, TNF) and catabolic factors may also play a more important role for these findings." (PMID 35847697, 2020). "Collectively, our results point to a novel mechanism by which both activin A and IL‐6 can contribute to cachexia and that this interplay may provide targets for treatment of cancer cachexia." (PMID 31436048, 2020).
cancer (continued). "In cancer cells, IL-6 functions as an upstream mediator of STAT3 signaling pathway." (PMID 32545648, 2020). "The IL6-JAK-STAT3 pathway plays a crucial role in oncogenesis of diverse cancers." (PMID 32883226, 2020). "Interestingly, an IPA analysis showed that different regulated genes were positively associated with the invasion and migration process in cancer cells: VCAN, SPARC, IL6, MMP14, IL4R, ICAM, TIMP1 and IGF2." (PMID 32848147, 2020). "In breast cancers, activated cancer-associated fibroblasts (CAFs) regulate the BCSCs and support stem-cell-like characteristics through factors such as monocyte chemotactic protein-1 (CCL2), IL6, IL8, and high-mobility group box 1 (HMGB1)." (PMID 32883003, 2020). "The availability of PLOD2 is one way by which IL-6 and leptin may influence collagen re-organization to create a “highway” for cancer cell migration and invasion to promote metastasis." (PMID 32033341, 2020). "Finally, we sought to assess the potential effects of SB203580 and IL-6 on the cancer stem cell (CSC) population of PLum-AD and PLum-AI." (PMID 32790767, 2020). "IL-6 and TLRs activate STAT3, a key transcription factor that regulates genes implicated in cell proliferation, cell cycle progression, cell survival, and angiogenesis in cancer." (PMID 33180876, 2020). "Besides being the major alarm signal in the human body, IL-6 plays a dominant role in various types of cancer." (PMID 32864098, 2020). "In this study, we showed that nintedanib could suppress cancer-related cytokines, particularly, IL-6, IL-8 and VEGF." (PMID 32015511, 2020). "IL6 has been shown to mediate its diverse biological functions, such as normal cellular growth and an immune response, through the activation of STAT3, and the dysregulated secretion of IL6 is known to play a crucial role in the pathogenesis of various diseases, including cancer." (PMID 31936675, 2020). "Except for IL-6, all of these cytokines were specifically detected only in co-cultures of UniCAR T-cells with STn+ cancer cells in the presence of αSTn or αSTn-IgG4 TMs, with a significantly higher amount of secreted cytokines for the αSTn-IgG4 TM in comparison to the αSTn TM." (PMID 32370811, 2020). "The cancer cells in the coculture system demonstrated an upregulation of integrin β6, which could be antagonized via neutralizing IL-6 antibody." (PMID 32855767, 2020). "Neonatal cancer cells promote platelet production and activation by secreting active substances such as interleukin-6, while activated platelets secrete vascular endothelial growth factor, platelet-derived growth factor, and transforming growth factor-β to promote cancer angiogenesis." (PMID 32211444, 2020). "This aspect should, however, be better studied because while the role of IL-6 in the modification of iron metabolism through hepcidin is well established, its role in immune system modulation is different in the various phases of cancer progression." (PMID 32269279, 2020). "IL‐6 promotes the proliferation, survival, and metastasis of cancer cells to enhance angiogenesis." (PMID 32810392, 2020). "IL-6 has an important role in chronic inflammatory diseases and may play a role in cancer development." (PMID 33202561, 2020). "Subsequently, we examined whether increased IL-6 signaling could effectively induce the differentiation of this cell line as a possible approach for cancer therapy." (PMID 33227992, 2020). "Therefore, IL-6 appears in several disease processes such as cardiovascular, autoimmune, cancer and in septic disorders." (PMID 33371296, 2020). "For instance, it correlated with spleen mass and serum IL-6, another strongly altered responses in cancer, showing that Serpina3n may reflect the inflammatory state in various tissues." (PMID 32599075, 2020).
cancer (continued). "Though catabolic drivers in the skeletal muscle of cachectic patients remain poorly characterized, IL‐6 is thought to contribute to human cancer wasting and elevated circulating IL‐6 has been shown to be increased in NSCLC patients and associated with reduced survival." (PMID 31930715, 2020). "During cancer progression, high levels of both IL6 and ILR6 have been reported." (PMID 32957689, 2020). "Next, we determined whether SC-induced IL6 signaling functioned through gp130 expressed on the membrane of cancer cells." (PMID 32308766, 2020). "MVs released by cancer cells may contain various proteins that regulate immune responses, including chemokine receptors, proinflammatory cytokines such as IL-1 or IL-6 and cytokine receptors such as TNFR1." (PMID 32488850, 2020). "Cancer cells produce soluble factors, such as cytokines—for example, interleukin-6 (IL-6), IL-11, tumor necrosis factor alpha (TNF-α), and receptor activator of nuclear factor kappa-Β ligand (RANKL)—that activate osteoclastogenesis, leading to bone degradation." (PMID 33659950, 2020). "In cancer, nuclear expression of YAP1 and its role in carcinogenesis may be linked to the inflammatory state induced by interleukin-6, which directly induces the activation of activating Src family kinase." (PMID 32218280, 2020). "CXCL7 was induced, in turn, by cancer cell production of IL-6." (PMID 33371274, 2020). "IL-6 stimulates cancer cell proliferation and epithelial-to-mesenchymal transition." (PMID 33114676, 2020). "The effects of exercise on cancer growth were mediated via a direct regulation of natural killer cells by a mechanism that involved epinephrine-dependent mobilization of natural killer cells to the circulation and an IL-6-dependent redistribution to tumors." (PMID 32393961, 2020). "Several studies have revealed the IL-6-driven EMT process in various types of cancers." (PMID 32570756, 2020). "However, it is known that PDAC is an inflammatory cancer and patients show an increase in a certain number of cytokines, including IL-6." (PMID 31936786, 2020). "It is known that IL-6 is a critical cytokine involved in cancer and inflammation." (PMID 32944387, 2020). "However, a dysregulation of IL-6 production and/or persistently increased IL-6 expression plays a pathological role in the development of various inflammatory diseases and cancers, thus IL-6 is a double-edged sword for the host." (PMID 32870935, 2020). "In addition to chemokines, CAFs also release several cytokines from the interleukin (IL) family, such as IL-6, able to promote the invasion of cancer cells into the surrounding matrix." (PMID 32466591, 2020). "Pin1 has been reported to enhance the IL‐6/STAT3 pathway in different cancer types." (PMID 32347623, 2020). "Moreover, this study demonstrated that inflammatory cytokines such as IL-6, enable a subpopulation of cancer cells to display a hybrid epithelial/mesenchymal phenotype by enhancing Notch-Jag1 signaling and increasing the CSC population." (PMID 32605277, 2020). "myCAF is a CAF subpopulation with an elevated expression of αSMA that are located adjacent to cancer cells, whereas iCAFs, which are located further away from cancer cells, exhibit low αSMA expression and are characterized by the secretion of inflammatory mediators such as IL‐6." (PMID 32931156, 2020). "It is worth noting that cancer cells can express factors such as multiple copies in T-cell malignancy 1 (MCT-1) or yes-associated protein 1 (YAP), which activate IL-6 expression, thus promoting CSC expansion and increasing their frequency independently of macrophages." (PMID 33371274, 2020). "In addition, a constitutive expression of IDO in human cancer is sustained by an autocrine signal mediated via STAT-3 activation by proinflammatory cytokine IL-6 and AHR activation by tryptophan catabolites such as kynurenine." (PMID 32384638, 2020).
cancer (continued). "The activation of NF-κB signaling and induction of a target gene, Il6, were shown to promote the survival of cancer cells by protecting them against stress-induced cell death during the progression of inflammatory cancers, such as HCC and colitis-associated cancer." (PMID 32098370, 2020). "Moreover, targeting IL-6 sensitized anti-PD-L1 treatment in a colorectal preclinical model highlighting the potential role of IL-6 in cancer immunotherapy." (PMID 32655895, 2020). "The therapeutic modulation of IL-6 could increase the sensitivity of malignant tumors to radiotherapy." (PMID 33149212, 2020). "Meanwhile, some literatures have reported that PYK2 could regulate the release of IL-6 in different diseases such as cancer and inflammation related diseases." (PMID 32802115, 2020). "In addition, IL-6 is a critical factor which is detected at high levels and shown to be deregulated in cancer." (PMID 32922544, 2020). "In addition, adipocytes co-cultured with BC cells induce the expression of IL-6 in cancer cells, resulting in the phosphorylation of effector kinase CHK1 and the acquisition of a radio-resistant phenotype in BC cells." (PMID 32850459, 2020). "Both TNF-α and IL6 are known to have complex effects and dual roles in cancer." (PMID 33123499, 2020). "Besides direct cell-cell contact, cancer cells can activate fibroblasts to initiate an inflammatory response, promoting the expression of IL-6." (PMID 32855767, 2020). "Reports showed that several non-Smad signaling pathways could be activated by TGF-β, such as PI3K/AKT and IL-6 signaling, leading to resistance to various cancer treatments." (PMID 32984004, 2020). "A high NLR in bladder cancer positively correlates with determinable concentrations of IL-6 and IL-8 as well as with their Treg expression in peripheral blood, which emphasizes a systemic dependence between neutrophil infiltration in cancer and the secretion profile of cytokines." (PMID 32488850, 2020). "More importantly, other than cancer signaling pathways, immune processes such as IL-2 and IL-6 signaling pathways, INF-α and INF-γ response, and complement activity were dominantly associated with TBX22low status (14 terms were significant GSEA results, 13 were immune- or cancer-related processes)." (PMID 33392186, 2020). "Combination of PGE2 and IL-6 seems to be crucial for immune evasion in cancer." (PMID 31811337, 2020). "Due to these properties, IL6 plays an important role in several cancers, including GB." (PMID 33153019, 2020). "Indeed, it appears that the suppression of PGC-1α is a key event in the progression of cancer cachexia and is directly related to elevations in circulating IL-6." (PMID 33584337, 2020). "IL-6 is one of the cytokines whose expression is controlled by NF-κB for cancer cell survival." (PMID 32098370, 2020). "Our group demonstrated that Bazedoxifene suppressed IL‐6/gp130 signalling in cancer cells but its effect on myocardial pathology induced by pressure overload is still unknown." (PMID 32164044, 2020). "Along the same lines of the IL-6 effect in the cancer model, IL-6 could induce up-regulation of proliferation in CRSwNP in the case of “wounded” epithelium." (PMID 32209102, 2020). "Additionally, interleukin-6 plays an important role in the regulation of metabolism, in neural development and survival, and in the development and maintenance of various cancers." (PMID 32864098, 2020). "Majority of the studies that were also conducted demonstrated that for patient with indefinite cancer symptoms IL-6 might be used as a bed-side test since it correlated with the clinical characteristics of the patient." (PMID 32961987, 2020). "In cancer cells, IL-6 upregulates VEGF expression by the JAK/STAT3 signaling." (PMID 33123472, 2020).
cancer (continued). "The systemic inflammatory response from cancer cells promotes the infiltration of neutrophils, which benefits cancer progression via secreting interleukin-2 (IL-2), interleukin-6 (IL-6), interleukin-10 (IL-10), tumor necrosis factor α (TNF-α) and vascular endothelia growth factor (VEGF)." (PMID 32510138, 2020). "In endometrial cancer, CAFs promote cancer cell proliferation via the secretion of CXCL12 or IL-6." (PMID 33050576, 2020). "A few reports related the reduction of IL-6 to a targeted therapy for cancer." (PMID 32411334, 2020). "Interestingly, we found that IL-6 drives PD-L1 expression on MM cells, in agreement with recent reports from preclinical models and patient samples in other cancers." (PMID 32922390, 2020). "Some cytokines have also been used for cancer therapy, such as IL-8 and IL-6." (PMID 32508884, 2020). "Consequently, elevated concentrations of IL-6 have been observed in various diseases including autoimmune diseases and cancers, and the cytokine itself modulates the immune response during chronic inflammation." (PMID 32488850, 2020). "Serum level of TMAO was found to synergize the pro-inflammatory effects of Helicobacter pylori infections on gastric epithelial cells, through the increase in the expression level of pro-inflammatory genes such as IL-6 and chemokine ligands, which play roles in cancer progression." (PMID 32947866, 2020). "IL-6 is one of the well-studied biomarkers in cancer cachexia." (PMID 33334063, 2020). "Thus PTPRM suppresses STAT3 signaling in DDIAS-knockdown cells, suggesting that DDIAS promotes the IL-6–mediated STAT3 signaling in malignant cancer cells by inhibiting the PTPRM function." (PMID 31900385, 2020). "A positive feedback between IL-6 and miR-21 has been reported, where IL-6 secreted by M2 macrophages induces miR-21 expression in cancer cells, leading to the release of EVs packed with miR-21 which acts on the M2 macrophages further increasing the secretion of IL-6." (PMID 32927431, 2020). "Finally, cancer-associated fibroblasts (CAF) can also alter tumor iron metabolism, as fibroblast IL-6 secretion was shown to foster cancer cell hepcidin expression which supported iron retention in cancer cells in breast cancer spheroids." (PMID 33287315, 2020). "The present study provides novel insights into the interplay between activin A and IL‐6 secretion from cancer cells that may be important for the development of future therapeutic strategies to reverse cancer cachexia." (PMID 31436048, 2020). "Additionally, when LLC cells that express high amounts of IL-6 are used as an experimental cancer model, there is a reduction in survival." (PMID 33233839, 2020). "Additionally, elevations in ferritin, high-sensitivity C-reactive protein, erythrocyte sedimentation rate, procalcitonin, prothrombin time, interleukin-2 (IL-2) receptor, and interleukin-6 (IL-6) were observed in cancer patients." (PMID 32522278, 2020). "Elevated IL6 levels may also be a consequence of a feedback loop between cancer and myeloid cells, as least for LNCaP and THP-1 cells." (PMID 32316245, 2020). "IL-6 has a remarkable systemic effect, culminating, by the failure of metabolism, in severe psychological and mental problems, and finally leading to the death of the cancer patient." (PMID 33114676, 2020). "Several of the gene sets are associated with oncogenesis, progression, and metastasis of cancer, such as mitotic spindle, hypoxia, Kras signaling up, PI3K-AKT-mTOR signaling, IL6-JAK-STATS3 signaling, mTORC1 signaling, TNF- α signaling via NF- κB, inflammatory response, and Myc targets v1." (PMID 33194434, 2020). "Prx-1 exerts DNA-damage-associated functions, increasing the production of proinflammatory mediators, including nitric oxide (NO) metabolites, tumor necrosis factor-α (TNF-α), and interleukin-6 (IL-6), and is also induced by radiation in various types of cancer cells in vitro." (PMID 33316778, 2020).